IL6 (interleukin 6)
Diseases named in the same sentence as IL6 in open-access papers (continued):
Sharing a sentence is not in itself a finding about the gene and the disease.
colon carcinoma (continued). "PTX-3 is mainly induced by NF-κB and proinflammatory cytokines, such as IL-6 and TNF-α in breast and colon cancer." (PMID 33776564, 2021). "Dexmedetomidine suppressed the rapid increase of cytokine, TNF-α, and IL-6 levels in gastric cancer patients and decreased IL-6 and CRP levels and the inhibition of T-lymphocyte subsets in colon cancer patients undergoing radical surgery." (PMID 34300310, 2021). "These experimental data confirmed that miR-155-5p functioned through IL-6 and then regulated ZC3H12B, thus affecting immune escape of colon cancer." (PMID 33718596, 2021). "The regulations of IL-6 production via the phosphatidylinositol 3-kinase (PI3K)-Akt pathway and p38 mitogen-activated protein kinase (MAPK) were demonstrated in colon cancer and myofibroblast cells." (PMID 34948304, 2021). "On the other hand, IL-6 can induce STAT3 phosphorylation in colon cancer cells with overexpressed RAB3C, which promotes the migration of colon cancer cells." (PMID 33718596, 2021). "The results of recent study have revealed that pro-inflammatory cytokines including IL-6 and TNF-α decreased CYP27B1 expression in colon cancer cells." (PMID 34208589, 2021). "In tumorigenic cells, ET induced tumor angiogenesis via increased IL-6 and VEGF production by stromal fibroblasts isolated from colon cancer and enhanced lung metastasis in a xenograft mouse model." (PMID 34868543, 2021). "(A) IL‐6 and (B) TNF‐α secretion were analyzed by ELISA in stage II and IV colonic tumor tissue and precancerous tissue." (PMID 33882644, 2021). "As expected, the treatment of colon cancer cells by LPS induced inflammatory response resulting in the substantial increase of COX-2 and IL-6 produced by the cells (respectively)." (PMID 34204704, 2021). "Recently, a new network was discovered between IL-6 and YAP1, which led to an increase in colonic tumor formation." (PMID 33807620, 2021). "miR-155-5p was transferred by M2 macrophage-derived exosomes into colon cancer cells, where miR-155-5p targeted ZC3H12B, which in turn negatively regulated the stability of IL-6 mRNA." (PMID 33718596, 2021). "CyCl treatment suppressed the expression of NF-κB target genes, such as NF-κB inhibitor α and δ, TNF-α, IL-6, and IL-8, in TNF-α treated colon cancer cells." (PMID 32230772, 2020). "IL-6/STAT3 signalling plays an important role in the rate of occurrence and development of colon cancer." (PMID 33082817, 2020). "In the CAC model, FLCWK synergized with 5-FU to inhibit the phosphorylation of STAT3, preventing IL-6/STAT3 signal transduction and thus further inducing apoptosis and inhibition of colon cancer cell proliferation." (PMID 33082817, 2020). "We found that colon cancer tissue in the mouse model as well as LPS-stimulated CT26.WT cells were in an inflammatory state as indicated by increased expression of TNF-α, IL-6 and adhesion molecules." (PMID 32210720, 2020). "In the functional study of core down‐regulation factors, it was found that IL6, GM‐CSF, IL11, CCL3 and S100A8/9 increased the viability of colon cancer cell lines and decreased the apoptosis rate of colon cancer cells with irradiation and chemical treatment." (PMID 31650683, 2020). "Cytokines that promote colon tumor development include the tumor necrosis factor (TNF), interleukin 6 (IL-6), interleukin 1B (IL-1B), and interleukin 8 (IL-8)." (PMID 32983990, 2020). "In the functional study of core down‐regulation factors, it was found that IL6, GM‐CSF, IL11, CCL3 and S100A8/9 increased the viability and decreased the apoptosis rate of colon cancer cells with irradiation and chemical treatment." (PMID 31650683, 2020). "In summary, we provided evidence that MSI-N1014 suppressed the major colon cancer stemness markers, LGR5 and β-catenin, and oncogenic signaling, such as mTOR and IL-6; it also prevented cancer cell-mediated CAF transformation." (PMID 32560222, 2020).
colon carcinoma (continued). "It has been shown that proinflammatory cytokines, such as interleukin-6 (IL-6) and tumor necrosis alpha (TNF-α), inhibit vitamin D metabolism in colon cancer cells." (PMID 32422882, 2020). "The expression of GP130, IL-11, IL-11 receptor α (IL-11Rα), IL-6, IL-6 receptor (IL-6R) and STAT3 activation were examined by western blot in DLD-1, HCT-15, and HCT-116 colon cancer cell lines." (PMID 30736824, 2019). "Here we employed human recombinant IL-6 to activate the IL-6/STAT3 pathway and found that it promotes colon cancer stemness in an FRA1-dependent manner." (PMID 30804456, 2019). "Two specific major targets include the upregulation of miR-101b and miR-455, which in turn led to decreased levels of IL-6 and TNF-α; these are pro-inflammatory proteins known to be promoters of colon cancer." (PMID 30959836, 2019). "Incremental expression of proinflammatory cytokines such as NF-κB and TNF-α and overactivation of IL-6/STAT3 passage have been well determined to exercise definitive implication in the pathogenesis of UC and colon cancer." (PMID 31772601, 2019). "Neutralization of IL-6 activity by anti-IL-6 antibody diminished its effect on inducing STAT3 activation in CT26 cells and their invasion activity, revealing a role of IL-6 in STAT3 activation and colon cancer cell growth." (PMID 30931933, 2019). "Here the authors identify TRIM27 as a positive regulator of IL-6-induced STAT3 activation through the formation of JAK1-STAT3 complex, thus impacting inflammation-induced colon cancer development." (PMID 30143645, 2018). "As expected, IL-6 enhanced the expression of MMP9, while metformin reduced the IL-6-enhanced expression of MMP9 in colon cancer cells." (PMID 30308035, 2018). "We showed that IL-6 induced EMT, which promotes colon cancer progression, and that STAT3 phosphorylation was involved in this pathway." (PMID 30308035, 2018). "In conclusion, genomic data analysis revealed that metformin can reduce IL-6 signaling, EMT, and colon cancer metastasis." (PMID 30308035, 2018). "For the first time, we show that MMM induce MK2 phosphorylation in colon tumor cells and when added to tumors treated with MK2 inhibitor induce production of the known MK2-downstream cytokines IL-1β, IL-6, and TNF-α." (PMID 30298062, 2018). "IL-6 gene expression was significantly increased in colon adenoma, CRC, colon carcinoma, rectal AC, colon mucinous carcinoma, colon AC, cecum AC, and rectosigmoid AC." (PMID 28725043, 2017). "One example is the role of S1P in the IL-6/STAT3 pathway (interleukin 6/signal transducer and activator of transcriptional factor STAT3), which is involved in IBD pathophysiology and colon cancer development." (PMID 28362332, 2017). "Similar to our results, it has been reported that stimulation with IL-6 will up-regulate the expression of ZEB1 and down-regulate ZO1 expression in colon cancer cells." (PMID 29383101, 2017). "We showed that exogenous IL-6 led to the increased generation of colon tumor spheres with concomitant elevated YAP1 expression, establishing a novel link between YAP1 and IL-6 network." (PMID 28241877, 2017). "MUC2 plays a role in the progression of colon cancer, and reduced MUC2 protein expression correlates with increased interleukin-6 (IL-6) expression." (PMID 28725043, 2017). "We used immunohistochemistry to detect the protein expression of MUC2, IL-6, and CD68 in serial sections of colon cancer tissues." (PMID 28725043, 2017). "We observed that IL-6 knockdown decreased the RAB3C-enhanced migration/invasion ability of colon cancer cells, thus indicating a critical role of the RAB3C-IL-6 axis in promoting the metastatic potential of colon cancer cells." (PMID 28784136, 2017). "We demonstrated that LY5 inhibited constitutive Interleukin-6 (IL-6)-induced STAT3 phosphorylation, STAT3 nuclear translocation, decreased STAT3 downstream targeted gene expression and induced apoptosis in liver and colon cancer cells." (PMID 26883202, 2016).
colon carcinoma (continued). "Elevated levels of IL-1β, IL-6, TNF-α, MCP-1 and PGE2 are therefore accepted as major prognostic indicators for the progression of colon cancer." (PMID 27507058, 2016). "It was found that both IL-6 and TNF-α interact to induce TNF-R2 expression and function in colon cancer cells, suggesting that a specific microenvironment of multiple cytokines is required to induce TNF-R2, as found in IBD or IBD associated CRC." (PMID 26896068, 2016). "There is good evidence that IL-6 family cytokines (IL-11 and IL-6) and STAT3 signaling are important for the survival and proliferation of colon tumor cells in mouse models." (PMID 25890501, 2015). "Regulation of the IL-6/STAT3 pathway by p38α impinges upon tumor cell proliferation and survival in mouse models of colon cancer." (PMID 25890501, 2015). "Once activated, NFκB up-regulates the transcription of various proinflammatory mediators including TNF-α, IL-1β, IL-6, COX-2 and iNOS, which typically are overexpressed in colon cancer." (PMID 25763529, 2015). "D. candidum increased the body weights of the mice compared with the control group, and reduced the levels of the serum proinflammatory cytokines, IL-6, IL-12, TNF-α and IFN-γ, compared with the colon cancer control group." (PMID 24396476, 2014). "IL-6–JAK–STAT signaling path has been found to be important for tumorigenesis in various tumor models such as ovarian, lung, bladder, breast and colon cancers." (PMID 24670367, 2014). "NF-kappaB is also known to facilitate angiogenesis, invasion and metastasis in colon cancer tumor cells by up-regulating vascular endothelial growth factor (VEGF), cyclooxygenase 2 (COX-2), interleukine (IL)-6 and matrix metalloproteinases (MMPs)." (PMID 25157570, 2014). "HCT-116 colon cancer cells were treated with CPT, OXP, and IL-6 separately or in combination in a time and dose-dependent manner and examined for phosphorylated and non-phosphorylated RKIP and STAT3 via Western blot analysis." (PMID 24098947, 2013). "To investigate the specific inhibition of GO-Y030, we detected the phosphorylation of STAT3, STAT1, or STAT6 induced by IL-6, IFN-γ, or IL-4 in HT29 colon cancer cell lines." (PMID 21694723, 2011). "C-reactive protein (CRP), albumin, IL-1α, IL-1β, IL-6, IL-8, IL-10, TNF-α, midkine, VEGF-A, VEGF-C, leptin, adiponectin, and ghrelin serum levels are studied in 126 colon cancer patients and 36 healthy subjects." (PMID 20920199, 2010). "A more detailed picture of clonal sensitivity towards modulators of IL-6 was obtained when IL-1β, PGE2, 1,25-(OH)2D3, and 17β-E2, singly or in appropriate combinations, were added to colon carcinoma cell cultures." (PMID 18205904, 2008). "In MakA-treated CT26 colon cancer cells, most cytokines stayed undetectable except for marginally induced Il6 and Ifnb1, neither of which was significantly altered in vivo." (PMID 41326332, 2025). "This complex interaction between colon cancer and tumor microenvironment facilitates transformation of normal fibroblasts into CAFs by modulating IL-6, enhancing VEGF release and promoting tumor growth." (PMID 40677714, 2025). "UdF at a concentration of 200 μg/mL significantly reduced the release of IL-1β by cancer cells after a 24 h incubation, but none of the tested extracts affected the release of IL-6 and IL-10 in human colon tumor cells." (PMID 39519642, 2024). "For example, in orthotopic tumor models of breast and colon cancer cells, GPR4 is activated after pH reduction and promotes tumor growth and pathological angiogenesis through p38-mediated secretion of interleukin-6 (IL-6), IL-8, and vascular endothelial growth factor-A (VEGF-A)." (PMID 38505262, 2024). "A previous study reported that the PGE2/IL1 cytokine network mediates the interaction between TA-MSC and colon cancer cells, in which PGE2 and cytokines derived from cancer-educated MSC enhance IL1, IL6, and IL8 production in cancer cells, which in turn enriches the cancer stem cell population." (PMID 38515582, 2024).
colon carcinoma (continued). "Furthermore, SFN displayed significant antioxidant and chemopreventive activities by inhibiting the IL-1β-induced expression of IL-6 and the subsequent MAPK/AP-1/STAT3 signaling in HT-29 colon cancer cells." (PMID 38671854, 2024). "As the IL-6/STAT3 pathway is an important pathway that regulates the progression of colon cancer, inhibition of this pathway by Luteolin provided new insight into the therapeutic potential and mechanisms of Luteolin for colon cancer treatment." (PMID 36992138, 2023). "Chenodeoxycholic acid and ursodeoxycholic acid inhibit IL-1, IL-6, and TNF-α at certain concentrations by inhibiting the activity of monocytes, while lithocholic acid downregulates NF-κB activity via vitamin D receptors in colon cancer cells." (PMID 36819995, 2023). "Importantly, GPR30 or Akt siRNA reversed the increased expression of IL-6 and TGF-β in HCT116 and HT29 colon cancer cells in response to estradiol stimulation." (PMID 37055842, 2023). "This may indicate that D. maritima bulb extract induces apoptosis in colon cancer cells through the TNF-α, IL-6, and caspase-8 activation pathways." (PMID 36770882, 2023). "IL-6 is overexpressed in CRC patients and is correlated with a larger tumor size, the occurrence of liver metastasis and reduced survival rates, as this interleukin is also a potent stimulator of colon cancer cell proliferation." (PMID 35682971, 2022). "For instance, RNA-seq dataset reanalysis of colon tumours demonstrated that TAMs, in which NO signalling was increased, also exhibited enhanced inflammatory pathway activation, including TNF-α and IL-6 signalling, when compared to macrophages from normal areas." (PMID 35660630, 2022). "Taken together, the AC serum effectively relieved the indicators of inflammation and down-regulating the expression of colon cancer biomarker CXCL8 as determined by bioinformatics analysis but has no impact on another pro-inflammatory chemokine IL6." (PMID 35922850, 2022). "Besides, our results showing nuclear translocation of CypB and following co-localization with lncPVT1 in response to IL-6 treatment indicate potential roles of lncPVT1 and CypB in mediating activation of STAT3 in colon cancer cells." (PMID 36266267, 2022). "In addition to the downregulation of cytokines, the inflammatory stimulators IL-6 and SAA3P were also downregulated in MTA1-overexpressing CT26 mouse colon cancer cells." (PMID 35350571, 2022). "The serum NF-κB, TNF-α, IL-6, PTX-3, PCT, and serum CRP concentration was significantly higher, and the serum sTRAIL concentration was significantly lower in the patients with breast and colon cancer than in healthy controls." (PMID 33776564, 2021). "IL-6 produced by the tumor-bearing host can aggravate the immunosuppression in the tumor microenvironment by inhibiting antitumor cells including CD8 + T cells, thus leading to the metastasis and colonization of colon cancer cells." (PMID 33688358, 2021). "The circulating IL-6, TNF-α, TRAIL level in breast and colon cancer may be a biomarker of postoperative progression or recurrence." (PMID 33776564, 2021). "Our initial results indicated that ZC3H12B affected immune escape through IL-6, but whether miR-155-5p promotes immune escape through the regulation of ZC3H12B in colon cancer remained unclear." (PMID 33718596, 2021). "Specifically, in colon cancer there is often an increase in the soluble receptor of IL-6 rather than the membrane receptor, leading to an increase in the activation of STAT and hence the activation of pro-survival proteins." (PMID 34944867, 2021). "Notably, our findings are in accordance with the results of the current study which shows elevated levels of TNF-a, IL-6, and VEGF in patients suffering from colon cancer." (PMID 34096454, 2021).
colon carcinoma (continued). "Indeed, it has been found that infiltrating macrophages secrete inflammatory mediators CCL2, IL-1α, IL-6, and tumor necrosis factor-α (TNF-α) to promote the proliferation of colon cancer cells." (PMID 33224886, 2020). "The results strongly indicated that FLCWK could increase the phosphorylation of STAT3 with 5-FU, inhibit signal transduction of IL-6/STAT3, and further induce apoptosis and antiproliferative effects in colon cancer cells." (PMID 33082817, 2020). "We thus concluded that FLCWK could synergize with 5-FU and inhibit suppressed IL-6/STAT3 signalling by attenuating the phosphorylation of STAT3 and further exerting apoptosis-inducing and antiproliferative effects on colon cancer cells." (PMID 33082817, 2020). "The role of tRXRα expression in myeloid cells was also illustrated by increased macrophage infiltration and mRNA expression of IL-6, IL-11, and TNFα in colon tumor tissues from LysM-tRXRα but not in LysM-RXRα mice." (PMID 30931933, 2019). "We therefore speculated that IL-6 trans-signaling initiated by the EGF-R mediated IL-6 secretion and the ADAM17-mediated IL-6R shedding might contribute to colon cancer formation in the APCmin/+ model." (PMID 31694340, 2019). "IL-6-mediated activation of STAT3 in colon cancer cell lines was shown to occur in conjunction with the phosphorylation (inactivation) of RKIP, leading to poor prognosis of colon cancer stage II patients." (PMID 30149591, 2018). "Several meta-analyses have reported that inflammatory markers such as IL6 and CRP are associated with an increased risk of colon cancer but not of rectal cancer." (PMID 28051997, 2017). "In colonic tumors, lack of vanin-1 is associated to higher levels of PPAR and to a reduction in IL-6 production and STAT3 activation, whose levels correlate with tumor size." (PMID 28448444, 2017). "This analysis identified downregulation of MUC2 and overexpression of IL-6 in colon cancer but not in normal colon tissue, and this expression pattern was correlated with poor survival of colon cancer patients." (PMID 28725043, 2017). "However, the immunosuppressive environment of tumors in AOM/DSS treated mice completely abolished the expression IL-6 and CXCL1, suggesting that colon cancer also affects the helminth-specific immune response." (PMID 28938014, 2017). "Whereas IL-6 induced STAT3 phosphorylation in the colonic cancer cell lines, primary non-malignant intestinal organoids did not respond to IL-6 classic signalling." (PMID 27869785, 2016). "In the intestinal epithelial cells IEC-6 and colon cancer cells HCT-116, IL-6 expression and its signaling were assessed with SHH inhibitors and levels of other inflammatory mediators, proliferation, apoptosis, tumorsphere formation, and tumorigenesis were also measured." (PMID 26716648, 2016). "Interestingly, the reduced levels of IL-6 mRNA observed in the PDXs upon p38 MAPK inhibition correlated with reduced phosphorylation of STAT3, an important regulator of colon tumor cell proliferation and survival." (PMID 25890501, 2015). "The active Crohn’s disease patients (ac-food, ac-EN and ac-DF) showed a significantly higher level of TNF-α and a non-significantly higher level of IL-6 than that of the Crohn’s disease patients in remission (re-EN and re-DF) and colon cancer patients (can)." (PMID 26140540, 2015). "Moreover, there is evidence that IL-6 and STAT3 signalling are important for the proliferation of tumour cells in mouse colon cancer models." (PMID 26079427, 2015). "Therefore, we employed RNA interference (RNAi) to suppress MUC2 expression in mouse colon carcinoma cells, and evaluated the effects of MUC2 suppression on IL-6 production and tumor growth." (PMID 25322805, 2014).